TRAP1 (TNF receptor associated protein 1)
Diseases named in the same sentence as TRAP1 in open-access papers (continued):
Sharing a sentence is not in itself a finding about the gene and the disease.
tumor (continued). "Another study has found that two oncogenic Myc proteins (c-Myc and N-Myc) transcriptionally control the expression of the TRAP1, thus regulating the proper folding and function of OXPHOS complex II and IV subunits, reducing ROS production, and enabling oxidative bioenergetics in tumour cells." (PMID 34769108, 2021). "In addition, TRAP1 maintains ERK1/2 activity as a mitochondrial chaperone; in turn, ERK-dependent phosphorylation of TRAP1 inhibits SDH, which is conducive to shifting the metabolic characteristics of tumor cells toward the Warburg phenotype." (PMID 33575209, 2020). "With the discovery that the molecular chaperones HSP90 and the closely related protein TRAP-1 locate to the mitochondria of tumor cells, but not most normal cells, the Altieri group pioneered the development of a series of mitochondria-targeted HSP90 inhibitors called Gamitrinibs." (PMID 28484090, 2017). "An important limitation of our approach that must be kept in mind is that the query proteins Hsp90α or Trap1 were absent both from the mammary epithelial cells, i.e. the tumor cells, and the stroma at the primary tumor site and all the way to the metastatic sites in the lung." (PMID 28407697, 2017). "In particular, the oncogenic TRAP1 was shown to interact with succinate dehydrogenase (SDH), inhibiting succinate oxidation and inducing a pseudohypoxic response (i.e., HIF1 activation in normoxic conditions), but also by shielding tumor cells from ROS-induced PTP opening and death." (PMID 27289382, 2016). "Taken as a whole, these observations support the notion that TRAP1 quality control and antiapoptotic protein network is a potential molecular target for anticancer therapy and that BRAF-addicted tumors are a suitable and attractive tumor cell model to evaluate this novel therapeutic strategy." (PMID 26084290, 2015). "An inverse correlation between TRAP1 expression and tumor grade was also observed, suggesting that the absence of TRAP1 might favor ROS-dependent tumor invasiveness, possibly enhancing activity of respiratory complex IV." (PMID 25564869, 2014). "This is in accord with a model by which the absence of TRAP1 would prompt an increase in ROS levels at later tumor stages, contributing to a more aggressive phenotype by increasing cell motility and genomic instability of the neoplasm." (PMID 25564869, 2014). "Furthermore, interference with the function of TRAP1 may result in the death of tumor cells but does not affect normal cells." (PMID 33575209, 2020). "Hence, the absence of TRAP1 could display its anti-tumor effect not only by inducing SDH and down-regulating the intracellular concentration of the oncometabolite succinate, but also by increasing NAD+/NADH ratio and the consequent SIRT3 activity via complex I induction." (PMID 35393510, 2022). "By binding an allosteric site in TRAP1, HDCA inhibits TRAP1 but not Hsp90 ATPase activity in a concentration-dependent manner to enhance SDH activity, thus decreasing tumor cell proliferation and tumorigenic growth." (PMID 33575209, 2020).
infection (5 papers, 2017 to 2024). The state of being infected such as from the introduction of a foreign agent such as serum, vaccine, antigenic substance or organism. "vs. TGF-β1 induction group, 72 h), which cloud be significantly reversed by the Lv-TRAP-1 infection in HFLS (p < 0.01." (PMID 37920489, 2023). "vs. TGF-β1 induction group), and the effect of oltipraz were reversed by Lv-TRAP-1 infection (p < 0.01, vs. oltipraz pretreatment + TGF-β1 induction group." (PMID 37920489, 2023). "To identify the effects of TRAP1 on HG-induced injuries, we performed TRAP1 overexpression and knockdown experiments by lentiviral infection in NRK-52e cells." (PMID 32215175, 2020). "Moreover, the effects of oltipraz were blocked by Lv-TRAP-1 infection in HFLS (p<0.01, vs oltipraz pretreatment + TGF-β1 induction group)." (PMID 37920489, 2023). "Babesia bovis TRAP2, 3, and 4 surface proteins may be important for parasite development in the mammalian host and tick midgut lumen, whereas B. bovis TRAP1 may play a key role in the infection of tick ovary cells." (PMID 36363765, 2022). "Nonetheless, B. bovis TRAP1 could be used as an antigen for vaccine development to disrupt parasite transmission by tick vectors and prevent mammalian host infection." (PMID 36363765, 2022).
neurodegenerative disease (5 papers, 2012 to 2025). A disorder of the central nervous system characterized by gradual and progressive loss of neural tissue and neurologic function. "As TRAP1 is a mitochondrial protein chaperone with several pro-survival roles, it represents an interesting target in neurodegenerative diseases, as mitochondrial dysfunction and protein misfolding are thought to play a pivotal and early role in pathology." (PMID 35163711, 2022). "Together, these results show that TRAP1 may be a potential therapeutic target for neurodegenerative diseases such as ALS, where mitochondrial dysfunction has been shown to be an early marker of pathogenesis." (PMID 35163711, 2022). "Moreover, TRAP1 may contribute to the regulation of normal brain development and/or the onset of neurodegenerative diseases." (PMID 23284813, 2012).
retinopathy (2 papers, 2023 to 2024). "Since these factors are also increased in DR patients and implicated in the pathogenesis of retinopathy, the reduced retinal pathogenesis observed upon TRAP1 inhibition might be associated with decreases in the levels of these factors, as well as those of VEGF, ANGPTL4, and ANG2." (PMID 37983591, 2024). "Thus, in diseased hypoxic retinal cells, expression of TRAP1 is induced to close mPTPs and maintain mitochondrial calcium storage, which is essential for activation of HIF1α and development of retinopathy." (PMID 37983591, 2024). "TRAP1 knockout dramatically reduced retinal pathogenesis in mouse retinopathy models in vivo, and TRAP1 inhibitors reduced aberrant vascular changes in the retinopathy mice, identifying TRAP1 inhibitors as a potent treatment for ischemic retinal diseases." (PMID 37071341, 2023).
TRAP1 also shares sentences with these, for which no sentence is quoted: bladder cancer (3 papers); thyroid carcinoma (3); Alzheimer disease (2); colon adenocarcinoma (2); COVID-19 (2); adenocarcinoma (1); allergies (1); animal disease (1); asthma (1); autism (1); benign prostatic hyperplasia (1); colon adenomatous polyps (1); colorectal (1); diabetic retinopathy (1); endometrial cancer (1); HIV-1 infection (1); Intellectual disability (1); kidney damage (1); kidney injury (1); leukodystrophy (1); lung adenocarcinoma (1); lung diseases (1); mesothelioma (1); metabolic disease (1); migraine headaches (1); myeloma (1); myocardial infarction (1); non-Hodgkin lymphoma (1); Nystagmus (1); oral cancer (1).
A further 16 diseases each share a sentence with TRAP1 in 1 paper.